IL13 (interleukin 13)
Diseases named in the same sentence as IL13 in open-access papers (continued):
Sharing a sentence is not in itself a finding about the gene and the disease.
cancer (continued). "An in-depth analysis of the interactome and the phosphoproteome of PTP1B discovered a critical role for the transcription factor SHN3 in regulating IL-13/PTP1B-mediated proliferative and invasive capacities in cancer cells." (PMID 37963919, 2023). "A deeper characterization of the PTP1B molecular networks should contribute to elucidating the molecular connections between IL-13, IL13Rα2, PTP1B, and other mediators in inflammation and cancer progression." (PMID 37963919, 2023). "For example, lesion cells produce IL-13, and PSC and cancer cells can produce IL-4, both factors that drive M1 to M2 polarization." (PMID 37638028, 2023). "When TH1 and TH2 cytokine levels in the serum and cancer tissues were compared, TH1 cytokines IL-2, TNF-α, IFN-γ, and IL-13 were significantly increased in patients compared to healthy controls." (PMID 34012451, 2021). "CD4+ T cell subsets, such as Th1, Th2, Th17, and regulatory T (Treg) cells, serve pivotal functions in cancer immunity, among which the Th2 subset of CD4+ T cells secretes IL-4, IL-5, and IL-13, and activates B cells to become antibody-secreting plasma cells." (PMID 35069553, 2021). "IL-4 and IL-13, produced by multiple components in the TME, mediate a wide range of functions in a variety of cancers through appropriate receptors." (PMID 33804263, 2021). "The expression profile of inflammation- and cancer-related genes (IL-1β, IL-8, TNF-α, IFN-γ, IL-6, NF-κB, and IL-13) were measured using qPCR." (PMID 37901256, 2021). "Under these conditions, a sequential action of IL-4/IL-13 and IGF-I targeting on macrophages and cancer cells, respectively, culminates in cancer progression." (PMID 34769439, 2021). "(a) Disease-free survival in pan-cancer TCGA cohort of 9502 patients from 33 cancers stratified by median MYC+TWIST1 expression (first KM curve) and median MYC+TWIST1+ CCL2+IL13 (second KM curve)." (PMID 31933479, 2020). "Further, in 33 human cancers (n = 9502) MYC and TWIST1 predict poor survival (p=4.3×10−10), CCL2/IL13 expression (p<10−109) and TAM infiltration (p<10−96)." (PMID 31933479, 2020). "In CRC cells, the binding of IL-13 to IL13Rα2 triggers STAT6-independent cellular pathways, promoting migration, invasion and survival of cancer cells through the scaffold protein FAM120A, which participates in the activation of FAK and the PI3K pathway." (PMID 32098194, 2020). "A study reported that the interactions between interleukin-13 and interleukin-13 receptor alpha 1 (IL13RA1) contributed to cancer cell growth and metastasis, and IL13RA1 expression was associated with poor prognosis in invasive BC patients." (PMID 33489894, 2020). "First, in 9502 patients with 33 different types of human cancer, the subset of tumors with MYC and TWIST1 predicts poor survival, CCL2/IL13 expression and TAM infiltration." (PMID 31933479, 2020). "Surprisingly, this study sheds light on the possible integration of IL-13/STAT6 axis and Hippo signaling through YAP1 in cancer progression in NASH." (PMID 32283835, 2020). "Next, we used cBioPortal to evaluate the correlations between the levels of FGL2 and the cancer-promoting cytokines measured above (IL-10, MMP9, CCL5, TIM-3, IL-13, VCAM1, M-CSF and FGF-7) in ESCA tissues." (PMID 33323552, 2020). "On the front of cancer cells, both TMZ-R and TMZ-S cells showed a significant increase in the M2 cytokines mRNA level of IL-10, IL-4, IL-13 and CCL2 as compared to their parental counterparts." (PMID 31462285, 2019). "Our findings demonstrate that IL-13 promotes EMT and cancer stem cell development in CRC cells, which contribute to CRC malignancy." (PMID 27533463, 2016). "IL-13Rα2, one of the IL-13 receptors, is highly expressed in some cancer cells, including GBM23 and OSCC24; therefore, targeting this receptor, such as CAR-T and IL13-PE, would be new strategy for these cancer patients." (PMID 27271009, 2016).
cancer (continued). "No histological toxicity was detected in association with IL-13-PE treatment in tissues such as the spleen, lung, and heart (data not shown), which thereby demonstrated the restricted targeting of the IL-13-PE cytotoxin to only the cancer cells and not the normal tissues." (PMID 23421960, 2013). "For instance, IL-4 and IL-13, increase the expression of 15-LOX-1 and -2 in a number of cell types, including monocytes/macrophages, T lymphocytes and several cancer cell lines." (PMID 19296842, 2009). "IL-6, IL-8, IL-12, IL-13, IFN-γ, MCP-1, MIP-1β and TNF-α were significantly more abundant in carcinoma than in normal breast." (PMID 17261184, 2007). "Using logistic regression analysis, we found salivary TGF-β and IL-13 levels as independent factors of cancer cachexia, while serum concentrations are not an independent factor." (PMID 39272892, 2024). "Previous reports indicate that the removal of MMP9 expression increases the secretion of IL-4 and IL-13 in the inflammation of respiratory airways, suggesting the existence of a self-regulatory loop between IL-13 and MMP9 expression to sustain cancer-enabling inflammation." (PMID 37963919, 2023). "For example, IL-10, IL-13, and TGF-β from cancer cells and macrophages induce angiogenesis." (PMID 35895109, 2023). "IL-13 effects on cancer inflammation and invasion have not been thoroughly investigated, despite IL-13 drives the expression of IL13Rα2, a promising therapeutic target for GBM and other tumors." (PMID 37963919, 2023). "In addition, elucidating the phosphorylation alterations ultimately regulated by PTP1B after treatment with IL-13 should identify novel signaling pathways, providing us with additional insights into the role of PTP1B in cancer invasion and inflammation." (PMID 37963919, 2023). "In vitro and in vivo functional characterization of C4 and D7 IL13-mutein CAR T cells showed decreased activation, degranulation, cytokine release, and cytolytic activity compared to WT and E12Y CAR T cells in the presence of IL13Rα1-expressing cancer cells." (PMID 35939683, 2022). "The addition of both E12K and R109K mutations into an IL13-based CAR also showed attenuated, but not abolished, recognition of IL13Rα1-expressing cancer cells relative to IL13Rα2-expressing cancer cells." (PMID 35939683, 2022). "These experimental findings may have translational relevance in cancer: there is the possibility that CSF1, in conjunction with basophil-derived IL-4/IL-13, might enhance the M2-like/TAM polarization of macrophage in TME." (PMID 36578500, 2022). "Consistent with IL-13 secretion from activated ILC2s, the frequencies of polymorphonuclear (PMN)- and monocytic (M)-MDSCs were also significantly elevated during the progression from micro- to macrometastatic cancer." (PMID 35805039, 2022). "This included decreased anti-inflammatory factors such as IL-4, IL-13, M-CSF and CXCL12 and antitumor factors SCF, FLT-3L and IL-25 that could contribute to cancer progression and metastasis." (PMID 34575976, 2021). "A new potential treatment modality for cancer could be dupilumab, an antibody targeting IL4Rα, a receptor subunit for IL4 and IL13." (PMID 34235145, 2021). "Further, our results suggest that Ccl2 and Il13 alone can enable a non-metastatic cancer to become metastatic, cell non-autonomously." (PMID 31933479, 2020). "Moreover, after receiving cancer treatment radioactivity in lung cells diminished and cancer promoting factors declined (VEGFR2, ICAM-1, bFGF, KC, TNF-α, IL-6, IL-12, IL-10 and IL-13) showing a diminution of metastatic competency of the exosomes." (PMID 32570802, 2020). "However, the contribution of IL-13/STAT6 and YAP1, together with serum AFP, are proven to have the upper hand in predicting cancer development in NASH." (PMID 32283835, 2020). "Moreover, in 33 different human cancers, expression of both MYC and TWIST1 predict survival, expression of CCL2/IL13 and M2-like TAM infiltration." (PMID 31933479, 2020).
cancer (continued). "Thus, MYC and TWIST1 predict poor survival, CCL2/IL13 expression and M2-like TAM infiltration in human cancers." (PMID 31933479, 2020). "Basophils reportedly interact with and stimulate B cells through CD40L and release of IL-4, IL-6, IL-13, BAFF, and histamine, all of which may augment B cell proliferation, survival and antibody responses against cancer." (PMID 32645919, 2020). "Therefore, IL-13/IL-13Rα2 use the PI3K/AKT/mTOR and MAP kinases signaling that, in turn, induces the activation of the AP-1 complex to promote human cancer metastasis." (PMID 32098194, 2020). "Our study agreed with this report, as higher serum IL-13 and polymorphism at STAT6 rs167769 were reported to be the strongest variables associated with cancer progression in NASH patients, regardless of their fibrosis stages." (PMID 32283835, 2020). "Whereas D1 peptide inhibited IL-13-mediated invasion in IL13Rα1-silenced or control cells in both types of cancer, Rα1 peptide did not." (PMID 30318506, 2018). "Interleukin-13 receptor α2 (IL-13Rα2) is a high-affinity receptor for the Th2-derived cytokine interleukin-13 (IL-13), and is overexpressed in several types of cancers as compared to low or absent expression in embryonic cells and normal tissues 6–11." (PMID 25767039, 2015). "The expression of IL-13Rα2, a unique receptor that binds IL-13 with high affinity and involved in signaling in cancer cells, is over expressed in cancer while its expression is mostly absent or low on other tissues except expression in testicular tissue." (PMID 23421960, 2013). "TSA treatment enhanced the cytotoxicity of IL-13-PE in IL-13Rα2-negative cancer cells (IC50 40-50 ng/ml with 5 μM TSA), but not in normal cells (IC50 > 1000 ng/ml with 5 μM TSA)." (PMID 21477288, 2011). "IL-13-PE inhibited protein synthesis in IL-13Rα2-positive cancer cells (IC50 between 10 and 50 ng/ml) without TSA, but not in IL-13Rα2-negative cancer cells nor normal cells (IC50 > 1000 ng/ml)." (PMID 21477288, 2011). "Interventions that activate this CD8+ T cell/TIM3/IL-13-to-macrophage/IL-10 pathway to boost endogenous pain resolution could provide a treatment for persistent CIPN, thereby improving quality of life of the growing number of cancer survivors." (PMID 35260535, 2022). "IL-4 was able to stimulate phosphorylation of STAT6 at significantly lower doses than IL-13 in the human epithelial carcinoma cell line A549, suggesting that STAT6 may not be the main downstream molecular target of IL-13." (PMID 35578342, 2022). "Indeed, the IL-13/IL13Rα2 signaling axis activates Src through PTP1B and then activates the Ras → Raf → MAPK cascade followed by the AP-1 transcriptional pathway in a number of human cancers." (PMID 33917458, 2021). "Their results suggest that surgical and metabolic response to an IA justify the adoption of an entirely laparoscopic approach performing a right colectomy for cancer, but the role of other inflammatory mediators, such as IL-1β, IL-10, IL-13, TNFα and insulin, was not considered." (PMID 33958669, 2021). "Interestingly, we found that TGF-β1, TGF-β2 and TGF-β3 mRNAs were all remarkably up-regulated in the co-cultured cancer cells and NFs using real-time PCR, whereas IL-4, IL-13, BMP2 and PDGF-bb mRNAs were not affected in these cells." (PMID 26857387, 2016). "Here we found that metformin significantly suppressed IL-13 induced M2-like polarization of macrophages, as illustrated by reduced expression of CD206, down-regulation of M2 marker mRNAs, and inhibition of M2-like macrophages promoted migration of cancer cells and endothelial cells." (PMID 26497364, 2015). "Unlike HMGB1, IFNA1, IFNA2, IL-2, KIR2DL3, IL-13 and NCAPG2 demonstrated an intuitive correlation in only a few cancer types." (PMID 36776838, 2023). "To further characterize the role of IL-13/PTP1B in cancer invasion and progression, we analyzed the phosphoproteome of PTP1B-silenced and control cells, treated or not with IL-13." (PMID 37963919, 2023).
cancer (continued). "IL-13/IL13Rα2 activation of PTP1B was independent of EGFR activation and was critical for migration and invasion of cancer cells." (PMID 32098194, 2020). "IL13 in CRC correlated inversely with lymph node metastasis and TNM due to its increasing expression in non-cancerous tissue, paralleling increasing cancer advancement." (PMID 32512917, 2020). "However with the exception of TGF-β, we found no consistent significant increases in IL-10, IL-4, Il-13, Il-6, GM-CSF, G-CSF, or VEGF in the blood that could account for the failure across cancer patients." (PMID 31462392, 2019).
inflammation (121 papers, 2007 to 2026). Aberrant reaction of the microcirculation characterized by movement of fluid and leukocytes from the blood into extravascular tissues. "Experimental depletion of Vγ1+ cells in an animal CRS model reduced eosinophilic inflammation and suppressed T2-associated cytokines (IL-4, IL-5, and IL-13) and GATA3 expression, indicating that defined γδ subsets can potentiate T2-biased inflammation." (PMID 41470145, 2025). "These originate from blue-green algae, a natural part of the fish’s diet, and have been shown to moderate type 2 eosinophilic inflammation, including a reduction in eosinophilic activation and migration and associated reductions in IL-13 levels." (PMID 39000027, 2024). "In IBD, the CD is thought to be caused mainly by the Th1 immune response, characterized by IFN-γ, TNF-α, and IL-12-mediated intestinal inflammation, while UC is associated with Th2 response, with IL-5 and IL-13 dominating in inflammation mediation." (PMID 36824689, 2023). "Alveolar epithelial cells are critical to the pathogenesis of pulmonary inflammation and fibrosis, which are associated with overexpression of type 2 cytokine IL-13." (PMID 29672593, 2018). "Allergic asthmatic inflammation is known to be caused by the secretion of a series of Th2 cytokines (IL-4, IL-5, and IL-13) and proinflammatory cytokines (TNF-α and IL-1β)." (PMID 24312355, 2013). "The acidic mammalian chitinase (AMCase) in particular has been found to be causative in lung inflammation and induced by IL-13." (PMID 24023952, 2013). "The results of this study provide further insight into the kinetics of cytokine expression in allergen-challenged airways, and for the first time in a large animal model demonstrate a Th2 polarized cytokine profile featuring IL-4 and IL-13 associated with allergen-induced airway inflammation." (PMID 26362930, 2015). "IL-5 and IL-13 are TH2 cytokines associated with the development of airway inflammation in mice and humans; the observed increase in these proinflammatory cytokines in Cbl-b−/− mice is suggestive of exacerbated TH2 cell responses to aerosol challenge during acute inflammation." (PMID 26635806, 2015). "Strikingly, both RAGE overexpression and SHS exposure also induced robust increases in Th2 cytokines IL-5 and IL-13—hallmarks of eosinophilic inflammation in CRSwNP." (PMID 41020862, 2025). "Our study demonstrates that the enzyme MMP-12 is upregulated in allergen-challenged mice and in IL-13-overexpressing mice exhibiting cytokine-driven airway inflammation." (PMID 40940719, 2025). "Local effects of blocking IL-13 signalling on eosinophilic airway inflammation in moderate-severe asthmatics was investigated in the MESOS and CLAVIER studies." (PMID 40604958, 2025). "Cytokines released by Th2 cells, such as IL-4, IL-5, and IL-13, promote the proliferation and activation of eosinophils, mast cells, and goblet cells in the airways, triggering and exacerbating airway inflammation." (PMID 40993641, 2025). "The results indicated that both treatments significantly reduced the number of CD4+CD44+ T cells, most of which were memory T cells, in addition to reducing lung inflammation and lower levels of Th2 cytokines, such as IL-4, IL-5, and IL-13." (PMID 39060348, 2024). "Several biologics have demonstrated therapeutic potential for the treatment of this pathology in which IL-4, IL-5 and IL-13 represent the major cytokines involved in the control of eosinophilic respiratory inflammation." (PMID 37763171, 2023). "HFD increased the levels of PA in mice, and subsequently enhanced IL-13-induced airway eosinophilic inflammation." (PMID 37287831, 2023). "Prior work has shown that expression of cathelicidin and β-defensin AMPs is decreased by the action of Th2 cytokines such as IL-4 and IL-13.10–12 However, the skin during Th2 inflammation still has a partial increase in host defense gene expression." (PMID 37167061, 2023).